FOXO1 (forkhead box O1)
Diseases named in the same sentence as FOXO1 in open-access papers (continued):
Sharing a sentence is not in itself a finding about the gene and the disease.
Insulin resistance (continued). "Specifically, hepatic insulin resistance leads to the activation of the forkhead transcription factor (FoxO1), which promotes the overexpression of bile cholesterol transport proteins Abcg5 and Abcg8, resulting in excessive cholesterol secretion into bile." (PMID 39944962, 2025). "Curcumin can reverse insulin resistance or protect RINm5F pancreatic β cells from apoptosis induced by nortriptyline by inhibiting the phosphoinositide 3-kinase/AKT/FOXO1 pathway and AKAP150/PKA/PP2B interaction, acting on diabetes caused by antidepressants." (PMID 40918536, 2025). "Upregulation of SIRT1 has been shown to activate PGC-1α and FOXO1 through deacetylation, thereby alleviating mitochondrial dysfunction, insulin resistance, and obesity in mice fed a high-fat diet." (PMID 41228560, 2025). "In the liver, insulin resistance promotes cholesterol secretion through ABCG5/8 induced aberrant expression of FOXO1." (PMID 40748974, 2025). "Conversely, upregulation of miR-146b and miR-21 decreases FOXO1 expression, suppressing hepatic glycogenesis and response to insulin resistance induction." (PMID 38805166, 2024). "In diabetic myocardium, conditions like hyperglycemia, insulin resistance, and metabolic disturbances such as elevated serum glucose or lipids can induce FoxO1 expression, shifting its function from antioxidant to prooxidant." (PMID 39206323, 2024). "Infliximab (anti-TNF-α monoclonal antibody) can reduce hepatic steatosis and fibrosis by upregulating the phosphorylation levels of AKT and FOXO1, thereby improving hepatic insulin resistance." (PMID 39021599, 2024). "This combination modulates the regulation of miR-27a-3p and miR-96–5p, directly affecting FOXO1 expression and improving hepatic gluconeogenesis and insulin resistance [53••]." (PMID 38805166, 2024). "A direct connection can be made between BA signaling and T2DM by FOXO1, a gluconeogenic transcription factor that should be inhibited by insulin signaling, but in insulin resistance paradoxically remains active." (PMID 38664391, 2024). "Our study unveils the role of miR-721 in regulating gluconeogenesis through KDM2A and FOXO1 under insulin resistance, pointing towards significant clinical and therapeutic implications for metabolic disorders." (PMID 38745315, 2024). "In H9C2 cells treated with high glucose, insulin resistance induced increased expression of FoxO1 and increased autophagy." (PMID 38113341, 2024). "Meanwhile, Akt can also inhibit hepatic glucose production and further improve the insulin resistance status by inhibiting the activity of transcription factors such as FoxO1 and reducing the expression of gluconeogenesis-related genes." (PMID 39845797, 2024). "PA stimulation also promotes the nuclear accumulation of p65 and its physical interactions with FoxO1, suggesting the potential involvement of PAQR3 in activating FoxO1 through the NF-kB pathway in insulin resistance." (PMID 38540730, 2024). "In the case of insulin resistance and diabetes, reduced growth signals and increased stress signals lead to weaker nuclear exportation mechanisms for FoxO1, resulting in increased FoxO1 transcriptional activity in cardiomyocytes." (PMID 39206323, 2024). "This indicates that targeting treatments related to the low-level phosphorylation of FOXO1 in insulin resistance can improve insulin sensitivity." (PMID 39021599, 2024). "On the contrary, insulin resistance compromises PI3K/AKT signaling to enhance FoxO1 nuclear retention and transcriptional activity." (PMID 38540730, 2024). "Taken together, we propose that the myocardin inhibition-insulin resistance-increased FoxO1 expression signaling axis plays a central role in promoting lipid and glucose metabolism disorder and the development of cardiomyopathy in Atp6v0d1AKO mice." (PMID 38505620, 2024). "In our study palmitate induced insulin resistance in hepatocytes significantly increased H3K36me2 levels on the promoter site of FOXO1." (PMID 38745315, 2024).
Insulin resistance (continued). "In male and ovariectomized (OVX) female mice, FoxO1 was found to be required for the improvement of estrogen on insulin resistance, which is through activation of ERα- PI3K-Akt-FoxO1 signaling, which is independent of IRS1 and IRS2." (PMID 36942499, 2023). "Upregulation of miR‐146b decreases Sirt1 gene expression and subsequent acetylation of FOXO1 in diabetic mice liver and HepG2 cells, in response to the insulin resistance induction and the suppression of hepatic glycogenesis." (PMID 37329278, 2023). "Insulin resistance can enhance biliary cholesterol secretion via dysregulation of the hepatic transcription factor forkhead box protein O1 (FOXO1) and has effect on the cholesterol transporters ABCG5 and ABCG8." (PMID 37455265, 2023). "Previous studies have revealed that Foxo1 participates in insulin resistance and β-cell failure in T2DM patients and leads to gluconeogenesis dysfunction and cell apoptosis." (PMID 37033250, 2023). "Because insulin resistance is associated with PI3K–AKT-FOXO1 axis, the phosphorylated AKT and FOXO1 were examined, and it was found that DKK1 decreased phosphorylation of AKT (Ser473) and FOXO1." (PMID 36410795, 2023). "In hepatocytes, insulin resistance induces abnormal expression of the transcription factor forkhead box protein O1 (FOXO1) through the ABCG5 and ABCG8 genes to promote cholesterol secretion." (PMID 37396166, 2023). "In male mice, heart insulin resistance caused by cardiac IRS1 and IRS2 ablation induces heart failure and gradually leads to death, which is rescued by cardiac FoxO1 deletion." (PMID 37960324, 2023). "IRS1/2 knock out mice induced insulin resistance, decreasing FOXO1 suppression and leading to hyper-active FOXO1." (PMID 37396164, 2023). "FOXO1 activity was significantly enhanced in the livers of old mice and FOXO1 inhibition improved insulin resistance, hepatic steatosis, and inflammation in old mice." (PMID 37602516, 2023). "Overall, these results suggest that increased FoxO1 activity in insulin resistance contributes to the decrease in skeletal muscle glucose uptake and utilization along with the increase in fatty acid uptake and oxidation." (PMID 37941908, 2023). "Activation of FoxO1 impairs hepatic mitochondrial function by controlling heme homeostasis, thereby contributing to insulin resistance-mediated hepatic mitochondrial dysfunction." (PMID 37960324, 2023). "Insulin resistance in T2D increases FoxO1 activation in metabolic tissues including liver, skeletal muscle, adipose tissue, pancreas, and brain, which underscores FoxO1’s potential clinical relevance." (PMID 37941908, 2023). "In summary, FoxO1 plays a pivotal role in insulin resistance-induced hyperglycemia, chronic inflammation, hepatic mitochondrial dysfunction, liver fibrosis, heart failure, and hypertension." (PMID 37960324, 2023). "Over the past decade, we have proven that FoxO1 is one of the key factors that link insulin resistance and metabolic disorders." (PMID 37960324, 2023). "β-cell GLUT2 is upregulated by forkhead box O1 (FoxO1), a key transcription factor that augments β-cell compensation for fat-induced insulin resistance in mice." (PMID 38229396, 2023). "We conclude that myeloid FoxO1 dysregulation, stemming from overnutrition and insulin resistance, promotes macrophage M1 polarization, and this effect triggers hepatic inflammation and catalyzes the evolution of NAFL to NASH in obesity." (PMID 35700043, 2022). "Inactivation of FOXO1 has been reported in islets of insulin resistance positive GIRKO mice and severely hyperglycaemic db/db mice." (PMID 34935260, 2022). "FoxO1 was markedly upregulated in tissue macrophages in the liver and adipose tissues, coinciding with the induction of proinflammatory profiles and insulin resistance in dietary obese mice." (PMID 35700043, 2022).
Insulin resistance (continued). "Under conditions of insulin resistance, FOXO1 remains active and continues to affect microsomal triglyceride transfer protein (MTTP) and apolipoprotein C-III (APO C-III), which is one of the proteins responsible for hypertriglyceridemia." (PMID 36232910, 2022). "Our findings along with previous results reinforce the idea that FoxO1 connects overnutrition and insulin resistance to abnormal macrophage activation, contributing to chronic low-grade inflammation and NASH in obesity." (PMID 35700043, 2022). "Increased FoxO1 activity, resulting from insulin resistance, acts to suppress M2 polarization in favor of macrophage M1 polarization in obesity." (PMID 35700043, 2022). "In the setting of insulin resistance, this results in more active FoxO1, followed by higher Cyp8b1 expression which in turn leads to increased CA synthesis." (PMID 34957857, 2022). "In insulin resistance, nuclear FoxO1 expression increases and coactivates with PGC-1α, thereby regulating downstream target genes to promote gluconeogenesis." (PMID 35198097, 2022). "In response to obesity or insulin resistance, FoxO1 activity is upregulated in hepatic and adipose tissue macrophages, contributing to hepatic inflammation and NASH." (PMID 35700043, 2022). "Studies have shown that pancreatic cancer cell-derived exosomes induce insulin resistance in C2C12 myotube cells through the PI3K/Akt/FoxO1 pathway." (PMID 36440209, 2022). "FOXO1 is an important regulator of pancreatic beta-cell function affecting pancreatic beta cells under conditions of insulin resistance." (PMID 36232910, 2022). "Several studies have shown that decreased insulin/PI3K/AKT signaling inhibits FOXO1 phosphorylation at the three sites (T24, S256, and S319), enhancing the subsequent nuclear translocation and activity of FOXO1, inducing insulin resistance." (PMID 35132380, 2022). "TMAO bound and activated the endoplasmic reticulum stress kinase PERK (a key sensor of intracellular stress), and then PERK induced FoxO1, which promoted insulin resistance and metabolic dysfunction." (PMID 35982495, 2022). "They improve insulin resistance by reducing hepatic glucose production and lipid accumulation through the activation of GSK3β and by suppressing both FOXO1 and SREBP transcription." (PMID 36159557, 2022). "Unchecked FoxO1 activity in hepatocytes, resulting from insulin resistance, is a contributing factor for glucose and lipid disorders in obesity and type 2 diabetes." (PMID 35700043, 2022). "The involvement of the FOXO1 transcription factor in the etiology of muscle insulin resistance in critical illness is mediated via increased pyruvate dehydrogenase kinase 4 (PDK4) transcription." (PMID 34769017, 2021). "It has also been shown that the long noncoding RNA Gomafu can increase Foxo1 expression to enhance hepatic insulin resistance by regulating miR-139-5p." (PMID 34725544, 2021). "Overexpression of SIRT1 is able to rescue obesity-induced insulin resistance in POMC neurons of mice where insulin-resistant nuclear FOXO1 has become constitutive." (PMID 33806509, 2021). "In mouse models of insulin resistance, GQD alleviated insulin resistance through silent information regulator 1 (Sirt1)-dependent deacetylation of forkhead box O1 (FOXO1)." (PMID 34025427, 2021). "Acute resistance exercise in obese patients with insulin resistance elevates Foxo1 mRNA expression levels in the skeletal muscle." (PMID 33955191, 2021). "Cai and coworkers reported that circHIPK3 promotes hyperglycemia and insulin resistance by acting as a sponge for miR-192-5p, which subsequently induces the expression of the forkhead box O1 (FOXO1) protein." (PMID 33708127, 2021).
Insulin resistance (continued). "Insulin resistance will decrease FOXO1 phosphorylation by insulin through PI3K-AKT, which would retain FOXO1 in the nucleus and prevent cytoplasmic ubiquitinoylation and degradation, resulting in increased expression of G6pc and Pck1." (PMID 33672754, 2021). "Overexpression of FoxO1 in the hypothalamus and pancreas accounts for obesity, insulin resistance, glucose intolerance and hyper-triglyceridemia." (PMID 34371822, 2021). "Both insulin resistance and oxidative stress can enhance the transcriptional activity of FOXO1 that can again contribute to the development of hyperglycemia and the production of ROS." (PMID 33289908, 2021). "Further computational studies dissected forkhead box O1 (FOXO1) regulation by mTORC1 and mTORC2 in the context of insulin resistance in T2D." (PMID 33544134, 2021). "We further found that Kir6.1 overexpression also improved cardiomyocyte dysfunction and up‐regulated the phosphorylation of AKT and FoxO1 in neonatal rat ventricular cardiomyocytes with insulin resistance." (PMID 33547878, 2021). "A recent finding showed that VDR-knockout mice showed insulin resistance with an increased FOXO1 expression in skeletal muscle." (PMID 34371843, 2021). "As a result, suppressing FOXO1 signalling can protect mice from HFD-induced insulin resistance by increasing insulin sensing regulator PPARγ." (PMID 34803738, 2021). "Further study revealed that insulin resistance suppressed the transcription factor foxhead box O1(FOXO1), whose downstream protein directly disrupted the mitochondrial ETC complexes." (PMID 34603021, 2021). "On the other hand, FOXO1 overexpression was found in patients with steatohepatitis and hepatic insulin resistance." (PMID 34034759, 2021). "β-cell compensation to insulin resistance is a proliferative response of the cells to growth factor-mediated signaling, and it requires nuclear exclusion of the forkhead box protein O1 (FOXO1)." (PMID 33806509, 2021). "Subsequent studies have shown that FoxO1 haploinsufficiency (FoxO1/2) defends diet-induced insulin resistance/diabetes by restricting the increase in the size of fat cells to promote the inhibitory effect of FoxO1 in adipose tissue." (PMID 33804729, 2021). "The altered nuclear-to-cytoplasmic ratio (N:C) of forkhead box O1 (FOXO1) in hyperglycemic MPCCs relative to normoglycemic MPCCs also implied abnormal influence of insulin on translocation of FOXO1 as seen in insulin-resistance patients." (PMID 34631680, 2021). "FOXO1 expression was reduced in patients with type II diabetes mellitus, and that the downregulation of FOXO1 induces insulin resistance states that qualitatively and quantitatively mimic the function of adipocytes from patients with type II diabetes mellitus." (PMID 32694937, 2020). "Especially in adipose tissue, the induced expression of FOXO1 ameliorates insulin resistance in the high-fat diet affecting the size of white adipocytes, while in brown adipocytes, it increases oxygen consumption and energy expenditure obesity." (PMID 33233382, 2020). "PA was used to treat L-O2 cells, as an insulin resistance model, and the SIRT1/FOXO1 pathway-associated proteins were measured." (PMID 32280711, 2020). "Insulin resistance in skeletal muscle mediated by forkhead box O1 (FOXO1), a critical negative regulator of insulin signaling, has been found to be linked to vitamin D." (PMID 33457118, 2020). "Among the top downregulated genes, we identified Foxq1, an established repressor of FOXO1, confirming the presence of insulin resistance in which FOXO1 is hyperactive." (PMID 33345777, 2020). "In agreement with this, a recent report concluded that an inhibition of the FOXO1/Pgc-1α pathway regulated hepatic gluconeogenesis and improved insulin resistance in rats fed with a HFD and insulin-resistant cells." (PMID 33348802, 2020). "In hepatic insulin resistance, the activity of FOXO1 is augmented, leading to the overproduction of hepatic VLDL." (PMID 33113859, 2020).
Insulin resistance (continued). "MNAM activates SIRT1 and inhibits acetylation of FOXO1, which in turn regulates insulin sensitivity in type 2 diabetic mice, leading to a reduction of hepatic glucose output and improvement of insulin resistance." (PMID 32280711, 2020). "Our previous work indicated that ZQR ameliorated hyperglycemia, insulin resistance and fatty liver by suppressing FOXO1 in the liver of T2DM rats." (PMID 32020874, 2020). "For example, circulating RNA HIPK3 (homeodomain-interacting protein kinase 3) can bind miR-192-5p with upregulation of transcription factor FOXO1 (forkhead box protein O1) leading to hyperglycemia and insulin resistance." (PMID 32993185, 2020). "The WB results suggested that VT improved insulin resistance, inhibited gluconeogenesis through the Akt/Foxo1/Pck2 signaling pathway, and reduced fatty acid synthesis via the SREBP1c/Fasn signaling pathways." (PMID 31096578, 2019). "Data presented here demonstrate that Zfp238, which is a co-repressor of Foxo1, likely plays a role as a metabolic regulator that can induce beiging with the potential capacity to counteract obesity and insulin resistance." (PMID 30677742, 2019). "We have presented in this study that C/EBP-α, FOXO1, PPAR-γ2 and IGFBP-2 have an interesting association in insulin resistance associated with obesity: their expression profile was found altered in adipose tissue in an insulin-dependent manner." (PMID 31547433, 2019). "Future studies are warranted to explore the roles of upstream factors in the FoxO1 signal transduction pathway in insulin resistance." (PMID 31853220, 2019). "FOXO1 actively participates in the development of insulin resistance by modulating the transcription of several transcription factors involved in adipogenesis and lipid and glucose metabolism." (PMID 31547433, 2019). "We show a down-expression of C/EBP-α and PPAR-γ2 and an overexpression of FOXO1 in VAT from high insulin resistance morbidly-obese (HIR-MO), and weak binding of PPAR-γ2 to RXR-α to form heterodimer in HIR-MO." (PMID 31547433, 2019). "In liver, the increased PI3K and phosphorylated AKT, the phosphorylated, and inactivated FoxO1, which regulates the expression of gluconeogenic gene and explains the effect of relieving insulin resistance of MBBP." (PMID 30800168, 2019). "Liver-specific deletion of Foxo1 in insulin-resistant (IR) mice significantly improved insulin sensitivity and glucose tolerance." (PMID 29459686, 2018). "The upregulation of FoxO1 in the liver has been associated with NASH, obesity, and insulin resistance, meanwhile hepatic FoxO1/3 knockout mice exhibit lower blood glucose levels and increased glucose tolerance." (PMID 30459740, 2018). "Metabolic stress induces constant activation of FoxO1 that results in blunted Akt signaling and insulin resistance." (PMID 30425649, 2018). "The aim of the present study was to examine the effect of RSV on blood glucose level, FOXO1 and FOXO3a expression in adipose tissue, insulin level, insulin resistance and serum superoxide dismutase (SOD) activity in rats with T2DM." (PMID 31565649, 2018). "For instance, FoxO1 protein levels were elevated in capillaries from skeletal muscle of mice fed a high-fat diet and the activity of endothelial FoxO1 correlated with adipose insulin resistance of obese subjects." (PMID 30511639, 2018). "Reduced FOXO1 function on the other hand was shown to protect against insulin resistance under a high fat diet in mice." (PMID 30558244, 2018). "Complementary to this, hepatocyte-specific IL6R, IL6, or STAT3 deficient mice develop increased gluconeogenesis and insulin resistance, as a result of G6pc upregulation, likely via a PI3K/FoxO1-independent pathway, as well as age-related obesity and steatosis." (PMID 30374109, 2018). "Previous studies showed that during adipose tissue FOXO1 gene silencing in transgenic mice, insulin resistance decreased and glucose tolerance improved." (PMID 31565649, 2018).